SLX1B (structure-specific endonuclease subunit SLX1B)
Description:
Catalytic subunit of the SLX1-SLX4 structure-specific endonuclease that resolves DNA secondary structures generated during DNA repair and recombination. Has endonuclease activity towards branched DNA substrates, introducing single-strand cuts in duplex DNA close to junctions with ss-DNA. Has a preference for 5'-flap structures, and promotes symmetrical cleavage of static and migrating Holliday junctions (HJs). Resolves HJs by generating two pairs of ligatable, nicked duplex products.
Synonyms: GIYD2; MGC5178
Gene: Protein-coding gene on chromosome 16 (29,454,533 to 29,458,223, forward strand). Ensembl gene ENSG00000181625.
Subcellular location: Nucleus
Subcellular location (Human Protein Atlas): Nucleoplasm
Pathways (Reactome):
DNA Repair: Fanconi Anemia Pathway; Resolution of D-loop Structures through Holliday Junction Intermediates
Gene Ontology:
Molecular function: 5'-flap endonuclease activity; crossover junction DNA endonuclease activity; protein binding
Biological process: DNA double-strand break processing involved in repair via single-strand annealing; DNA repair; double-strand break repair via homologous recombination; negative regulation of telomere maintenance via telomere lengthening; t-circle formation; telomere maintenance via telomere lengthening; telomeric D-loop disassembly; DNA replication; positive regulation of t-circle formation; DNA recombination; regulation of telomere maintenance
Cellular component: nuclear chromosome; nucleoplasm; Slx1-Slx4 complex; nucleus
Homologues: Orthologues: chimpanzee SLX1A (99% identical), dog SLX1A (81% identical), guinea pig Slx1a (77% identical), mouse Slx1b (76% identical), rat Slx1b (62% identical), tropical clawed frog slx1a (50% identical), zebrafish slx1b (44% identical), Drosophila melanogaster slx1 (40% identical), Caenorhabditis elegans slx-1 (35% identical). Paralogues in human: SLX1A (100% identical).
Diseases named in the same sentence as SLX1B in open-access papers:
SLX1B is named in the same sentence as 3 diseases in open-access papers, as found by Europe PMC text mining. Sharing a sentence is not in itself a finding about the gene and the disease. The quoted sentences say what the papers report.
mood disorder (1 paper, 2021). A cognitive disorder a disturbance in which the person's mood is hypothesized to be the main underlying feature. "In the phenome-wide association study, we found seventeen significant gene-trait pairs, including psychosis (NPIPB11, SLX1B) and mood disorders (SCARF2), and overall enrichment of mental traits." (PMID 34715901, 2021).
SLX1B also shares sentences with these, for which no sentence is quoted: psychosis (1 paper); schizophrenia (1).